RN7SL169P (RNA, 7SL, cytoplasmic 169, pseudogene)
Gene: Miscellaneous RNA gene on chromosome 5 (64,539,504 to 64,539,792, forward strand). Ensembl gene ENSG00000242547.
Homologues: Orthologues: chimpanzee Metazoa_SRP (98% identical), macaque Metazoa_SRP (96% identical). Paralogues in human: RN7SL1 (83% identical), RN7SL2 (82% identical), RN7SL3 (82% identical), RN7SL451P (80% identical), RN7SL664P (80% identical), RN7SL679P (80% identical), RN7SL230P (80% identical), RN7SL797P (80% identical), RN7SL769P (79% identical), RN7SL126P (79% identical), RN7SL15P (79% identical), RN7SL296P (79% identical), and 706 more.